TTPA (alpha tocopherol transfer protein)
Description:
Binds alpha-tocopherol, enhances its transfer between separate membranes, and stimulates its release from liver cells. Binds both phosphatidylinositol 3,4-bisphosphate and phosphatidylinositol 4,5-bisphosphate; the resulting conformation change is important for the release of the bound alpha-tocopherol (By similarity).
Synonyms: ATTP; AVED; TTP1; alphaTTP
Tractability: Small molecule: a structure with a bound ligand is known; a high-quality ligand is known; it has a high-quality binding pocket. PROTAC: its protein half-life has been measured; a small molecule that binds it is known.
Gene: Protein-coding gene on chromosome 8 (63,048,553 to 63,086,153, reverse strand). Ensembl gene ENSG00000137561.
Subcellular location: Cytoplasm
Pathways (Reactome):
Metabolism: Vitamin E transport
Gene Ontology:
Molecular function: lipid transfer activity; protein binding; phosphatidylinositol bisphosphate binding; phosphatidylinositol-3,4-bisphosphate binding; phosphatidylinositol-4,5-bisphosphate binding; vitamin E binding
Biological process: intermembrane lipid transfer; lipid metabolic process; vitamin E metabolic process; vitamin transport; negative regulation of establishment of blood-brain barrier; response to toxic substance
Cellular component: cytosol; late endosome; cytoplasm
Genetic constraint (gnomAD): Loss-of-function variants: 20 observed, 22.78 expected, observed/expected ratio (o/e) 0.88, 90% interval 0.62 to 1.28. The upper end of that interval is the gene's LOEUF score, 1.28, which puts it in group 5 of 6, group 1 being the genes least tolerant of losing a copy. Missense variants: 333 observed, 327.51 expected, observed/expected ratio (o/e) 1.02, 90% interval 0.93 to 1.11. Synonymous variants: 147 observed, 122.55 expected, observed/expected ratio (o/e) 1.2, 90% interval 1.05 to 1.38.
Homologues: Orthologues: chimpanzee TTPA (99% identical), macaque TTPA (98% identical), guinea pig TTPA (90% identical), dog TTPA (90% identical), mouse Ttpa (89% identical), rat Ttpa (89% identical), pig TTPA (73% identical), tropical clawed frog ttpa (65% identical), zebrafish ttpa (60% identical), Drosophila melanogaster CG10026 (28% identical), Caenorhabditis elegans C34C12.6 (22% identical). Paralogues in human: SEC14L5 (26% identical), SEC14L1 (25% identical), SEC14L3 (25% identical), SEC14L4 (25% identical), SEC14L2 (25% identical), SEC14L6 (22% identical).
Diseases named in the same sentence as TTPA in open-access papers:
TTPA is named in the same sentence as 22 diseases in open-access papers, as found by Europe PMC text mining. Sharing a sentence is not in itself a finding about the gene and the disease. The quoted sentences say what the papers report.
Ataxia (16 papers, 2009 to 2025). Ataxia refers to impaired coordination of voluntary muscle movement. "For example, mutations in the TTPA gene, which encodes α-TTP, lead to ataxia with vitamin E deficiency, a neurodegenerative disorder marked by low plasma α-tocopherol levels." (PMID 40444179, 2025). "Ataxia, due to vitamin E deficiency, can have various causes, such as mutations in the TTPA gene, which is responsible for the alpha-tocopherol transfer protein." (PMID 37759536, 2023). "Heritable mutations in the TTPA gene result in familial vitamin E deficiency, elevated indices of oxidative stress, and progressive neurodegeneration that manifest primarily in spinocerebellar ataxia." (PMID 35150738, 2022). "Resultant from two SNPs in the TTPA gene are two variants, E141K and R59W, which are associated with ataxia due to vitamin E deficiency." (PMID 34576251, 2021). "Ataxia with isolated vitamin E deficiency (AVED) is a rare autosomal recessive condition that is caused by a mutation in the alpha tocopherol transfer protein gene." (PMID 26989534, 2016). "In other cases, founder mutations are dispersed around the Mediterranean basin as illustrated by the c.744delA mutation in the TTPA gene of ataxia with isolated vitamin E deficiency and the splice site defects in megaloblastic anemia 1 and triple-A syndrome." (PMID 22908982, 2012). "Ataxia with isolated vitamin E deficiency (AVED) is caused by mutations in the alpha tocopherol transfer protein (TTPA) gene, mapped on chromosome 8q13 that codifies for a protein which binds alpha tocopherol and very-low-density lipoproteins (VLDLs) in the liver." (PMID 33733696, 2021). "The vital importance of vitamin E is best exemplified by mutations in the tocopherol transfer protein (TTPA) gene that—in both animals and humans—manifest as the heritable disorder ataxia with vitamin E deficiency (Ataxia with vitamin E deficiency(AVED); OMIM #277640)." (PMID 28672782, 2017). "In addition, we found no other nonsynonymous sequence changes in any of the other 16 genes in the mapping interval, including the TTPA gene, mutations in which are found in ataxia with vitamin E deficiency (AVED)." (PMID 19461874, 2009). "Ataxia with Vitamin E deficiency is an autosomal recessive disorder caused by mutations in TTPA, coding for the alpha-tocopherol transfer protein." (PMID 34925200, 2021). "Previous work in horses has used known human diseases and experimental mouse models of ataxia to exclude the most likely candidate gene, TTPA." (PMID 31936863, 2020). "Vitamin E deficiency has been associated with ataxia, and supplementation of vitamin E can rescue the neuromotor deficit in mice lacking alpha-tocopherol transfer protein." (PMID 38635907, 2024). "TTPA encodes the tocopherol transfer protein (TTP), which regulates the whole-body status of vitamin E. AVED is characterized by loss of proprioception, progressive spinocerebellar ataxia, low levels of vitamin E, and elevated oxidative stress." (PMID 28672782, 2017). "The role of αTTP in VE homeostasis is well documented: in rats, a diet deficient in α-tocopherol induces lower αTTP levels in the liver; mutations in the TTPA gene are related to ataxia in humans, which is a neurological dysfunction that includes vitamin E serum deficiency." (PMID 30518135, 2018).
Ataxia with vitamin E deficiency (2 papers, 2024 to 2025). Ataxia with vitamin E deficiency (AVED) is a neurodegenerative disease belonging to the inherited cerebellar ataxias. "In humans, TTPA mutations are responsible for AVED, a disorder previously known as familial isolated vitamin E deficiency (FIVE)." (PMID 39874248, 2025).
Alzheimer disease (1 paper, 2015). A progressive, neurodegenerative disease characterized by loss of function and death of nerve cells in several areas of the brain leading to loss of cognitive function such as memory and language. "We previously reported that Alzheimer disease (AD) model mice showed decreased insulin-degrading enzyme (IDE) levels in the cerebrum and accelerated phenotypic features of AD when crossbred with alpha-tocopherol transfer protein knockout (Ttpa-/-) mice." (PMID 26637123, 2015).
trichinellosis (1 paper, 2023). "We found that Ts-TTPA protein with trypsin domain identified swine sera at 13 dpi most quickly and is a candidate antigen for early stage detection of trichinellosis." (PMID 37884927, 2023). "The protein binds in extracellular vesicles of T. spiralis identified by 25 dpi serum; especially the Ts-TTPA protein with trypsin domain can be the fastest to identify swine serum at 13 dpi and is a candidate antigen for early stage detection of trichinellosis." (PMID 37884927, 2023).
cancer (2 papers, 2016 to 2023). A tumor composed of atypical neoplastic, often pleomorphic cells that invade other tissues. "These actions may stem from the influence of vitamin D on the expression of genes associated with collagen production, such as SHMT1, UGT1A6, and ITIH2.The anti-cancer properties of vitamin D are also supported by changes in KLHL3 and TTPA gene expression." (PMID 38203636, 2023).
neurological disorders (2 papers, 2021 to 2023). "Humans carrying mutations in the TTPA gene revealed a low α-Toc level in plasma and neurological disorders associated with elevated oxidative stress termed as ataxia with VE deficiency (AVED), indicating the importance of αTTP in regulating plasma α-Toc levels." (PMID 33920342, 2021).
peripheral neuropathy (1 paper, 2021). A disorder affecting the peripheral nervous system. "TTPA encodes for a protein responsible for the transport of alpha-tocopherol into the cells and its mutation causes a form of ataxia with isolated vitamin E deficiency, associated with peripheral neuropathy." (PMID 33923421, 2021). "Therefore, polymorphisms affecting SLC5A7 and TTPA are not directly involved in the damage caused by vincristine, but represent a predisposition to the onset of peripheral neuropathy." (PMID 33923421, 2021).
TTPA also shares sentences with these, for which no sentence is quoted: anaemia (2 papers); infection (2); malaria (2); Anxiety (1); ataxia telangiectasia (1); cerebral malaria (1); depression (1); endometrial cancer (1); familial isolated vitamin E deficiency (1); hepatoma (1); neuropathy (1); parasitemia (1); Sensorimotor neuropathy (1); triple-A syndrome (1); Usher syndrome (1).